SCN1A (sodium voltage-gated channel alpha subunit 1)
Diseases named in the same sentence as SCN1A in open-access papers (continued):
Sharing a sentence is not in itself a finding about the gene and the disease.
epilepsy (continued). "SCN1A, located at 2q24.3, encodes the α 1 subunit of the sodium channel and is one of the most important epilepsy genes in humans." (PMID 39202364, 2024). "This important finding further supports the underlying molecular mechanisms of SCN1A genetic variants in the pathogenesis of drug-resistant epilepsy in children." (PMID 38674283, 2024). "Despite the increased attention to SCN1A-related epilepsies, the diagnostic journey remains challenging and requires additional novel strategies and clinical advances focused on combining clinical examination with molecular diagnosis." (PMID 39119390, 2024). "One proband has a duplication encompassing the entire SCN1A gene, a well-established cause of Dravet syndrome and related epilepsies including GEFS+." (PMID 38101940, 2024). "Variants in SCN1A give rise to a wide range of epilepsy syndromes, ranging from mild familial febrile seizures (FEB), and genetic epilepsy with febrile seizures plus (GEFS +), to severe developmental and epileptic encephalopathy (DEE) or Dravet syndrome (DS)." (PMID 40217529, 2024). "Mutations in several NaV-α subunits were associated with epilepsy, including NaV1.1 (SCN1A), NaV1.2 (SCN2A), NaV1.3 (SCN3A), NaV1.6 (SCN8A), and NaV1.7 (SCN9A)." (PMID 39728106, 2024). "Dravet syndrome (DS), characterized by severe epilepsy, is often caused by mutations in the SCN1A gene." (PMID 38920691, 2024). "In the knock-out model, the Scn1a gene is completely inactivated, resulting in severe epilepsy due to the loss of sodium channel function, which is crucial for maintaining the balance between excitatory and inhibitory signals in the brain." (PMID 39452036, 2024). "Here, we provide an overview of studies investigating metabolic alterations in epilepsies caused by mutations in the SCN1A and KCNA1 genes, which are currently the most studied ion channel epilepsies in animal models." (PMID 37594756, 2024). "This study analyzed the characteristic spatial and frequency distributions of SCN1A mutations, aiming to provide important insight into the mutagenesis etiopathology of SCN1A-associated epilepsy." (PMID 40217529, 2024). "The importance of SCN1A lies not only in its possible causal role in epilepsy but also in its potential influence on the efficacy of AEDs." (PMID 36987424, 2023). "Analogous to the ictal cry associated with GTCS in epilepsy patients, an “ictal squeak” was observed in Scn1a+/− mice." (PMID 36811143, 2023). "In fact, of all known mutations of epilepsy genes, SCN1A mutations are the most diversely implicated in both hereditary and acquired seizure pathogenesis." (PMID 40217485, 2023). "Most Dravet syndrome and GEFS + cases have mutations in SCN1A, which suggests in the context of epilepsies, this channel plays a role." (PMID 40217485, 2023). "SCN1A mutations can result in a wide range of seizures, including Dravet syndrome and other pediatric epilepsies of variable severity, like generalized epilepsy with febrile seizures plus (GEFS+)." (PMID 38003469, 2023). "Since there is no approved causative treatment for such cases so far, more attention is being paid to gene therapy, particularly in the case of monogenic epilepsies, e.g., Dravet syndrome related to SCN1A mutations." (PMID 38003469, 2023). "The SCN1A genes (coding for the voltage-gated Na+ channel alpha subunit NaV1.1), which form the most relevant epilepsy gene family, appear to be associated with the outcome but not the development of the Panayiotopoulos syndrome." (PMID 37388546, 2023). "The SCN1A gene is strongly associated with epilepsy and plays a central role for supporting cortical excitation-inhibition balance through the expression of NaV1.1 within inhibitory interneurons." (PMID 37139072, 2023).
epilepsy (continued). "With regard to epilepsy diagnosis, SCN1A variant patients were chiefly diagnosed with DS (72.7%, 40 of 55), and the remaining patients were diagnosed with unclassified epileptic encephalopathy (EE), GEFS+, complex febrile seizure (CFS), FS+, and West syndrome." (PMID 38174099, 2023). "A similar circadian sudden unexpected death in epilepsy (SUDEP) mortality pattern was previously detected in the same Scn1a-deficient mouse model, implying the presence of a circadian vulnerability in this mutant mouse model." (PMID 37551713, 2023). "For example, loss of excitatory currents due to mutations in NaV1.1 (Scn1a) in Dravet Syndrome results in epilepsy." (PMID 36879321, 2023). "Genetic deficient animal models verified the important role of the SCN1A gene in epilepsy development." (PMID 37576022, 2023). "Modifying the gating properties of the SCN1A mutant can lead to an imbalance in excitatory to inhibitory neurotransmission in neural circuits, causing both SCN1A-associated epilepsies and comorbidities." (PMID 38203200, 2023). "For example, SCN1A mutation-related epilepsy had a disease onset of several months, its clinical presentation was mainly DS, and few patients showed febrile seizures; while sodium channel blockers generally caused symptoms to worsen." (PMID 38174099, 2023). "Given the surprising finding that SCN1A gain-of-function is associated with severe forms of epilepsy, a modeling study explored the impact upon network behavior of different forms of homeostatic plasticity that act to restore basal pyramidal cell firing rates." (PMID 37139072, 2023). "For example, epilepsy surgeries have less favorable outcomes in patients with pathogenic variants in ion channel genes such as SCN1A." (PMID 37834053, 2023). "For example, variants in sodium channel protein type 1 subunit alpha (SCN1A, NaV1.1) are the second-most common finding in cohorts of individuals with monogenic epilepsy." (PMID 36877742, 2023). "SCN1A/SCN2A/SCN8A variant-related epilepsy was generally manifested at an earlier age, while the SCN3A/SCN9A/SCN1B variant-related subtype showed a later age at onset." (PMID 38174099, 2023). "Nav channel mutations are related to epilepsy, including α subunits, such as Nav1.1 (SCN1A), Nav1.2 (SCN2A), Nav1.3 (SCN3A), Nav1.6 (SCN8A), and Nav1.7 (SCN9A), and the β subunit (SCN1B)." (PMID 38174099, 2023). "Cortical SD is frequently generated following brain injury, while less is understood about its potential contribution to genetic disorders of hyperexcitability, such as SCN1A-deficient epilepsy, in which febrile seizure often contributes to disease initiation." (PMID 37551713, 2023). "Results of the study report insignificant differences between epilepsy cases and the control group regarding the frequency of SCN1A-A3184G genotypes and allele." (PMID 37679850, 2023). "SCN1A, the Na+ channel gene with the largest number of epilepsy-associated variants (mostly Dravet syndrome caused by LoF), is less implicated in neurodevelopmental clinical phenotypes than the other Na+ channel genes." (PMID 37240836, 2023). "We previously demonstrated that reducing Scn8a expression is therapeutic in Scn1a+/− mice and in mice with epilepsy caused by loss of the potassium channel genes Kcna1 and Kcnq2." (PMID 37901435, 2023). "In family 3 and 4, a definite diagnosis of epilepsy was obtained in the affected individual (I-1) by finding the c.209del variant and c.5727_5734delTTTAAAACinsCTTAAAAAG variant in the SCN1A gene, respectively." (PMID 38025388, 2023). "A family history of febrile seizures and epilepsy in individuals with DS and de novo SCN1A mutations implies a polygenic mode of inheritance." (PMID 38203200, 2023). "Many of the insights derived from molecular-genetic studies of SCN1A channelopathies remain conceptually distinct from the defining pathophysiology of epilepsy: a neuronal network predisposed to generating bursts of synchronous or hyper-excitable activity." (PMID 37139072, 2023).
epilepsy (continued). "In SCN1A variant patients, anticonvulsants were effective in 89.1% (49 of 55) of patients, epilepsy was controlled in 25.5% (14 of 55), and the seizure frequency decreased in 63.9% (35 of 55)." (PMID 38174099, 2023). "SCN1A, which encodes the Nav1.1 subtype of the pore-forming α subunit of the VGSCs, has been identified with 200 epilepsy mutations." (PMID 40217485, 2023). "Herein, taking advantage of Trio-WES, we detected five novel SCN1A variants associated with clinical phenotype in five probands with epilepsy or twitching, respectively." (PMID 38025388, 2023). "In contrast to disorders caused by single gene mutations, ultra-rare SCN1A variants are thought to heighten the risk of common epilepsies associated with polygenic inheritance." (PMID 37139072, 2023). "The father’s sister with severe ID, in whom we also detected the c.2508C>A, p.(Aps836Glu) SCN1A variant has been suffering from epilepsy from the first year of life." (PMID 38250573, 2023). "Cav3.1 was previously identified as a genetic modifier of epilepsy in Scn1a+/− mice, as genetic knockdown of the Cav3.1-encoding gene Cacna1g was reported to ameliorate spontaneous seizures and improve survival." (PMID 37082241, 2023). "Analysis of the treatment responses in 55 patients revealed that CLB, KD, VPA, and TPM produced better efficacy in SCN1A variant-related epilepsy patients, LEV showed slight efficacy, and OXC and LTG were ineffective in controlling convulsions." (PMID 38174099, 2023). "Mutations in the voltage-gated sodium channel alpha subunit 1 (SCN1A) gene are the main monogenic cause of epilepsy." (PMID 38025388, 2023). "CRISPR/Cas9 in human iPSCs was first used in epilepsy to generate a loss of function SCN1A mutation in order to gain more knowledge on DS." (PMID 37719765, 2023). "The results revealed impairments in action potential generation in response to sustained current injection, confirming previous studies from in vitro rodent epilepsy models with SCN1A mutation." (PMID 36672274, 2023). "sodium channel, neuronal type 1, alpha subunit (SCN1A) mutation, known to be associated with a broad spectrum of infant/childhood epilepsy, was detected in four patients in the current study." (PMID 37628333, 2023). "A total of five cases of sudden unexpected death in epilepsy (SUDEP) occurred in patients with SCN1A, SCN2A, and SCN8A variants." (PMID 38174099, 2023). "The phenotypic spectrum of epilepsy varies substantially across the patients harboring pathogenic variants in SCN1A gene." (PMID 38025388, 2023). "SCN1A has been widely implicated in epilepsy with varying severity and both genetic and phenotypic heterogeneity." (PMID 35627139, 2022). "A recent meta-analysis including eight studies reported that Asian patients with epilepsy and the GG genotype of the SCN1A-A3184G polymorphism are at a higher risk of carbamazepine resistance." (PMID 36056404, 2022). "DS linked to the SCN1A gene shows a phenotype that is characteristic of DS diagnosis, and the term SCN1A-related epilepsy has been proposed." (PMID 35529330, 2022). "SCN1A is one of the most rigorously studied sodium channel genes in epilepsy, with hundreds of genetic variants identified." (PMID 36229510, 2022). "Mutations of SCN1A, which encodes the voltage-gated sodium channel Nav1.1, can cause epilepsy disorders such as Dravet syndrome (DS) that are comorbid with wide-ranging neurologic dysfunction." (PMID 35523580, 2022). "Both PTEN and SCN1A are established neurodevelopmental genes, with mutations recorded in association with several disorders, including ID, epilepsy, and ASD." (PMID 35205252, 2022). "SCN1A encodes the α-1 subunit of the NaV1.1 sodium channel and is strongly associated with epilepsy as one of the most important channelopathies." (PMID 35205252, 2022).
epilepsy (continued). "SCN1A is amongst the best studied genes in epilepsy: rare pathogenic variants cause a variety of types of epilepsy, often characterised by seizures provoked by fever, as seen in Dravet syndrome." (PMID 35551471, 2022). "Keeping in view the unsure role of SCN1A SNPs, we, for the first time in the Pakistani population, analyzed the association pattern of these SNPs in drug-resistant epilepsy." (PMID 35136380, 2022). "The first SCN1A mutation was found in epilepsy patients by 2000, but now many new SCN1A mutations have been identified making it the most common epilepsy-related gene." (PMID 36056404, 2022). "Since the first discovery of SCN1A gene associated with epilepsy in 2000, SCN1A has remained the most common and important epilepsy pathogenic gene." (PMID 35571373, 2022). "To date, the clinical spectrum of epilepsies related to SCN1A variants encompass various phenotypes, the most common being SMEI and SMEB, and a small proportion being GEFS+, including FS and FS+." (PMID 35571373, 2022). "SCN1A heterozygous mutations are associated with a broad phenotypic spectrum of epilepsies ranging from genetic epilepsy with febrile seizures plus (GEFS+) to DEEs." (PMID 35328054, 2022). "Intriguingly, animal studies have shown that dopamine levels are decreased in rat models expressing epilepsy linked Scn1A mutations, providing a functional link between the overexpression of Scn1A and reduced dopamine levels in the NPRL2 nKO model." (PMID 35165201, 2022). "Phenotypic rescue of mice with Dravet syndrome, the more severe form of epilepsy due to SCN1A variants with mostly LoF variants, has led to development of several gene therapy approaches including oligonucleotides and viral vectors." (PMID 35627139, 2022). "Patient iPSCs have been used for epilepsy phenotype model diseases associated with SCN1A-related encephalopathies." (PMID 36231081, 2022). "SCN1A variants lead to dysfunction of the sodium channel which initiates and propagates neuronal action potentials, thereby causing epilepsy." (PMID 35571373, 2022). "In Italy, three variants of SCN1A: rs6730344, rs6732655 and rs10167228 were reported to impact the drug resistance to epilepsy." (PMID 35801810, 2022). "Regarding genetic vulnerability to epilepsy, different types of mutation have been reported in SCN1A including frameshift, nonsense and splice site mutations." (PMID 35801810, 2022). "The first use of CRISPR/Cas9 technology in epilepsy was reported in 2016 to generate a loss of function SCN1A mutation in human iPSCs to gain insight into Dravet syndrome." (PMID 36552721, 2022). "We conclude that NPRL2 functions as an important regulator of mTORC1 activity that controls the expression of epilepsy-linked Scn1A expression to regulate the strength of neuronal APs." (PMID 35165201, 2022). "The twin sister of patient 28 with DS carrying the same SCN1A (p.Arg1892Ter) heterozygous mutation died from a sudden unexpected death in epilepsy (SUDEP) at the age of 16." (PMID 35663268, 2022). "WES analysis of the trio revealed the presence in the proband of two variants in epilepsy-associated genes, SCN1A (NM_001202435.1) and CSNK2B (NM_001320.5)." (PMID 36360260, 2022). "For example, do individuals with loss-of-function variants in SCN1A have an increased PRS for epilepsy relative to controls?" (PMID 35679801, 2022). "The spectrum of seizure disorders associated with SCN1A range from mild to intermediate presentations such as isolated febrile seizure or genetic epilepsy with febrile seizure plus." (PMID 36229510, 2022). "SCN1A mutations are some of the most common epilepsy-related genes, with nearly a hundred mutations reported to date." (PMID 36142719, 2022). "The SCN1A variant was validated using Sanger sequencing and it segregates with epilepsy with incomplete penetrance in family members with an available DNA sample." (PMID 35627139, 2022).
epilepsy (continued). "Pathogenic variants in SCN1A, which encodes the voltage-gated sodium channel α subunit Nav1.1, cause a spectrum of epilepsies including Dravet syndrome (DS), the most common developmental and epileptic encephalopathy." (PMID 35212623, 2022). "The first group is the studies that described the generation of patient-specific iPSC lines that carry genetic variants in genes associated with epilepsy, such as SCN1A, GNB5, LGI1, GRIN2A, KCNC1, or KCNA2." (PMID 36552721, 2022). "Although the literature has largely focused on SCN1A, cell lines derived from epilepsy patients with SCN2A and SCN8A LOF mutations have been developed for future studies." (PMID 35359577, 2022). "The SCN1A gene was first associated with genetic (formerly generalized) epilepsy with febrile seizures plus (GEFS+)." (PMID 35571373, 2022). "Mutations in the neuronal sodium voltage-gated channel, alpha subunit 1 (SCN1A) gene have been associated with epilepsy." (PMID 36056404, 2022). "Genes potentially associated with FS-related epilepsy include SCN1A, ADGRV1, SCN1B, SCN9A, GABRG2, GABRD, and CPA6." (PMID 35813073, 2022). "Despite the highly similar electro-clinical phenotypes of the enrolled patients, the results obtained through NGS-based tests revealed possible variants in the SCN1A gene and four other epilepsy-related genes (SCN1B, SCN2A, SCN9A, and SCL2A1)." (PMID 35886038, 2022). "On reviewing literature, several studies were carried out to detect the possible pharmacological implications of the SCN1A-A3184G polymorphism in epilepsy management." (PMID 36056404, 2022). "The SCN1A gene is considered the most important and relevant gene responsible for epilepsy for encoding the α-1 subunit of voltage-gated sodium channel mainly expressed in the brain." (PMID 35813387, 2022). "Several Biomarkers of SCN1A gene have been proposed as risk factor to drug response and drug resistant of epilepsy." (PMID 35801810, 2022). "While haploinsufficiency in NaV1.1 activity results in Dravet, milder SCN1A mutations lead to less severe and treatable epilepsies, such as Generalized Epilepsy with Febrile Seizures Plus (GEFS+) and benign febrile seizures." (PMID 35370551, 2022). "We summarized the basic information of forty-four SCN1A in-frame deletion variants and performed further analysis on six variants identified in our cases with epilepsy." (PMID 35359575, 2022). "The phenotypes of SCN1A associated seizure disorder are significantly heterogeneous over a continuous spectrum from mild to severe with both commonness and individuality." (PMID 35571373, 2022). "SCN1A mutations are associated with various forms of seizures and epilepsies on a wide spectrum of severity, including “isolated” febrile seizures as well as Dravet syndrome (DS), a developmental and epileptic encephalopathy of poor prognosis." (PMID 35250833, 2022). "SCN9A was proven to be both a cause of febrile seizure and variable epilepsy phenotypes and a partner with SCN1A in DS." (PMID 35663268, 2022). "With the researches of the pathogenic mechanism of SCN1A-related epilepsy, especially the functional changes and genetic modifiers, there are some novel therapeutic approaches that target seizure control through genetic modulation have emerged." (PMID 35571373, 2022). "So far, more than 1800 SCN1A variants have been identified in epilepsy, but few studies have investigated the function of these genetic defects." (PMID 35359575, 2022). "SCN1A, encoding the alpha 1 subunit of the sodium channel, is associated with a range of related epilepsy." (PMID 36237607, 2022). "In particular, pathogenic variants in SCN1A/NaV1.1 are responsible for several epilepsy syndromes including Dravet Syndrome (DS), a severe childhood form of epilepsy characterized by beginning with complex FS." (PMID 35625812, 2022). "Within SCN1A gene we found that the rs6432861 (p = 0.014) was in correlation with the risk of epilepsy." (PMID 35801810, 2022).